TYR (tyrosinase)
Diseases named in the same sentence as TYR in open-access papers (continued):
Sharing a sentence is not in itself a finding about the gene and the disease.
melanoma (continued). "In addition, our results demonstrate that E. camaldulensis flower essential oil decreases melanogenesis in melanoma cells by inactivating PKA and MAPK signaling pathways and inhibiting tyrosinase activity." (PMID 25961954, 2015). "Gp100, tyrosinase and TRP-2 are involved in melanin synthesis, while Mart1 has been found necessary for gp100 function, and these proteins are expressed in most melanocytes and melanomas." (PMID 25854582, 2015). "Fa-a and Fa-b significantly and Fc-a slightly reduced the tyrosinase activity, Fb-a and Fb-b significantly increased the tyrosinase activity of B16 melanoma cells, and Fd-a had a little or no inhibition effect on the tyrosinase activity." (PMID 25197307, 2014). "After 12 h, B16 melanoma cell treatment with CGA leads to an increase in melanin accumulation, however, after 48 h there is a decrease in melanin production which correlates broadly with a decrease in tyrosinase activity." (PMID 25157464, 2014). "The main ingredient in the hydrophobic fraction of licorice extract is glabridin, which inhibits tyrosinase activity in cultured B16 murine melanoma cells without affecting DNA synthesis." (PMID 23431351, 2013). "In murine B16 melanoma cells stimulated with α-melanocyte-stimulating hormone (α-MSH), CC-EO and cinnamaldehyde not only reduced the melanin content and tyrosinase activity of the cells but also down-regulated tyrosinase expression without exhibiting cytotoxicity." (PMID 24051402, 2013). "Real-time quantitative PCR revealed that UVB light exposure significantly increased TYR mRNA level by 270% in non-α-Syn-expressed A375 melanoma cells, whereas, there was no significant change in α-Syn-over-expressed A375 melanoma cells." (PMID 23028833, 2012). "These levels exceed those in G-361 melanoma cells while another RPE cell line D407 lacking pigmentation did not express tyrosinase mRNA." (PMID 22259223, 2012). "Similar dedifferentiation to the amelanotic phenotype appears in melanoma cells where tyrosinase is not properly sorted into melanosomes but is retained in the endoplasmic reticulum and thereafter degraded." (PMID 22259223, 2012). "Accelerating tyrosinase degradation by EDEM1 overexpression may lead to an efficient antigen presentation and enhanced elimination of melanoma cells." (PMID 22905195, 2012). "Given the apparent aberrant expression of typical melanocytic differentiation markers (such as TYR, MLANA), we chose to stain potential melanoma CTCs for pan-KRT, which is generally expressed in melanomas and has prognostic significance (particularly KRT18; see Discussion)." (PMID 22829910, 2012). "Compared with vitiligo patients, melanoma patients with vitiligo have been shown to have similar titers of antibodies to TRP-2, although they have significantly lower titers of antibodies directed against whole melanoma cells and tyrosinase." (PMID 21911918, 2011). "The TYR gene is expressed only in the specified cells and in many (but not in all) human melanomas and serves as a good marker of melanocyte differentiation." (PMID 22649681, 2011). "The MIA gene promoter is of special interest, since this gene, as opposed to the TYR gene, is expressed only in malignant melanoma cells but not in other cells of the melanocyte lineage." (PMID 22649681, 2011). "Nevertheless, our method did not detect previously identified melanoma antigens, such as gp100, tyrosinase, TRP-1 and TRP-2; instead, it detected completely different proteins." (PMID 20479946, 2010). "AZ combined with Tau inhibited the melanin production and tyrosinase activity of B16F10 melanoma cells without significant cytotoxicity." (PMID 20804622, 2010). "Melanoma differentiation antigens (MDAs) include tyrosinase, pMEL17/gp100, gp75/tyrosinase related protein (TRP)-1, MART-1/melan-A and dopachrome tautomerase/TRP-2 and represent ideal target antigens for melanoma immunotherapy, due to preferential expression in melanocytes and melanoma cells." (PMID 20844763, 2010).
melanoma (continued). "Gp100, tyrosinase, and TRP-2 were identified previously as melanoma antigens recognized by cytotoxic T cells from cancer patients, and TRP-1 was identified as a melanoma antigen recognized by IgG antibodies in the serum of a melanoma patient." (PMID 20479946, 2010). "Oxyresveratrol has been described to have a potent dose-dependent non-competitive inhibition on l-tyrosine oxidation by tyrosinase from mushroom and murine melanoma B-16, without suppression of tyrosinase synthesis or expression." (PMID 19865532, 2009). "The most widely known and expressed melanoma Ags are MART-1, NY-ESO-1, gp100, and tyrosinase." (PMID 20016802, 2009). "The three HLA-A2*0201+ patients who did not develop any detectable MART1-, gp100- and tyrosinase-specific CD8+ T cells also did not experience regression of their melanoma metastases." (PMID 18334033, 2008). "It was found that the overall gene combination was related to the melanoma distinction (Wilks Lambda = .057, p < .001) with the standardized canonical discriminant function coefficients being MART1 = .267, TYR = .420, TYRP1 = .361, TYRP2 = .595, and QPCT = .808." (PMID 16820060, 2006). "The discriminatory immunostaining pattern with the 'MCW Melanoma Cocktail' (a mixture of MART-1 {1:500}, Melan- A {1:100}, and Tyrosinase {1:50} monoclonal antibodies) allows intraoperative immunocytochemical evaluation of imprint smears of SLNs for melanoma metastases." (PMID 16999866, 2006). "In this study, tyrosinase mRNA expression has been prospectively evaluated, immediately after surgical treatment and during follow-up, in 110 stage III disease-free melanoma patients, with the aim of defining the relationship between the tyrosinase detection and the clinical course of the disease." (PMID 14562017, 2003). "Another probable explanation for the three patients who developed recurrent disease despite negative RT–PCR tests is that the recurrent melanoma was tyrosinase negative." (PMID 12107840, 2002). "Tyrosinase mRNA amplification by RT–PCR may be a useful tool for monitoring the efficacy of adjuvant treatment in stage IIB and III melanoma patients." (PMID 12107840, 2002). "The detection of minimal amounts of melanoma cells by tyrosinase reverse transcription polymerase chain reaction (RT-PCR) is seriously hampered by false negative reports in blood of melanoma patients with disseminated melanoma." (PMID 10576666, 1999). "Additionally, experiments using B16F10 melanoma cells demonstrated a dose-dependent reduction in melanin production, accompanied by a decrease in the expression of melanogenesis-related genes, including MITF, TYR, TRP-1, and TRP-2." (PMID 40565189, 2025). "Moreover, the exosomes had no toxic effects on B16F10 melanoma cells at concentrations of 1.78 × 109, 3.55 × 109, and 7.10 × 109 particles/ml, and they suppressed melanogenesis by reducing tyrosinase activity." (PMID 39809510, 2025). "Additionally, a cytotoxicity assessment for 4d utilizing the MTT assay on A375 human melanoma cells demonstrated its non-toxic properties within the effective range, indicating its potential as an excellent TYR inhibitor for further research." (PMID 40005101, 2025). "Also, CBD decreases melanin content in αMSH-treated murine melanoma cells without inhibiting tyrosinase activity, suggesting alternative mechanisms." (PMID 41008526, 2025). "The experimental results showed that the extract has a significant inhibitory effect on tyrosinase activity in mouse melanoma cells at concentrations of 50 and 100 μg/mL without inducing cytotoxicity, thus demonstrating the enzyme activity in a non-toxic manner." (PMID 40508280, 2025). "However, the results indicate that fisetin mainly decreases intracellular tyrosinase levels in human melanoma cells rather than functioning solely as a direct enzyme inhibitor." (PMID 41373883, 2025).
melanoma (continued). "An in vivo study by Fujii & Saito demonstrated that quercetin isolated from Rosa canina L. reduced melanin synthesis in B16 melanoma cells by inhibiting tyrosinase activity, without affecting cell viability, while oral administration of rosehip extracts decreased skin pigmentation in guinea pigs." (PMID 40427440, 2025). "Furthermore, in B16-F10 melanoma cells, Mb-ME suppresses melanogenesis by reducing melanin secretion and cellular melanin content, although it does not directly affect tyrosinase activity or the expression of key melanogenic regulators such as MITF and TYRP1." (PMID 40076896, 2025). "Notably, MiTF staining was positive in a few melanomas that failed to stain for either HMB‐45, S‐100, TYR, or Melan‐A which are the most commonly used melanoma markers." (PMID 40509563, 2025). "However, interestingly, the fraction showed no activity against human tyrosinase, and in A375 melanoma cells treated with a doxorubicin fraction, doxorubicin activity decreased." (PMID 39125044, 2024). "The most promising trial data so far is from the BioNtech Lipo-MERIT trial in which patients with advanced melanoma were given 8 RNA-LPX vaccinations with a vaccine encoding four classic melanoma tumour antigens (NY-ESO-1, Tyrosinase, MAGE-A3, and TPTE) with or without anti-PD1." (PMID 38223410, 2024). "In addition, PT can downregulate tyrosinase protein expression and demonstrate superior performance compared to resveratrol and resveratrol trimethyl ether in α-MSH-induced melanogenesis in mouse melanoma cells (B16-F10)." (PMID 39204367, 2024). "Subsequent in vitro experiments demonstrated that 10E-PDA significantly reduced melanin production and intracellular tyrosinase activity in α-MSH (melanocyte-stimulating hormone)-stimulated B16F10 melanoma cells without exhibiting significant cytotoxicity at concentrations up to 15 μM." (PMID 39765875, 2024). "B16BL6 melanoma cells were transfected with a negative-control siRNA or with a siRNA directed against tyrosinase for 24 h, which effectively diminished the expression level of tyrosinase mRNA." (PMID 39337478, 2024). "Therefore, the reduction in melanin content of melanoma cells after treatment with TIP2 and RF1 could be the combined effects from antioxidative, anti-tyrosinase, and ROS reduction mechanisms." (PMID 36834568, 2023). "In contrast to an oncogenic role for WNT10B in melanoma described previously, in a mouse cell line model of melanoma (B16F10), WNT10B reduced melanoma cell proliferation, induced cellular senescence, and enhanced tyrosinase (a marker of differentiation) activity in vitro." (PMID 36814601, 2023). "A previous study showed that the tyrosinase inhibitory ability of the ethanol extract of MB is the highest among the 16 kinds of legume ethanol extracts, and the extract also demonstrates a significant inhibitory effect on melanin production in B16F1 melanoma cells." (PMID 35369078, 2022). "Melanogenesis-related proteins (MRPs) including tyrosinase, TRP-1, TRP-2, gp100, and MART-1 are classified as major histocompatibility complex (MHC)-restricted tumor antigens, and specific peptides derived from processing of MRPs can activate T-lymphocyte responses against melanoma cells." (PMID 35359389, 2022). "Transcript levels of conventional melanocytic markers (e.g. SILV, MLANA, and TYR) which are known to be dominantly regulated by MITF4,51, and of MITF itself were significantly inversely correlated with DNA methylation in the cell lines and TCGA melanoma samples." (PMID 35810190, 2022). "Because enzymatic browning and melanogenesis may share a common mechanism including tyrosinase activation, we tested the effects of maclurin on UVB-induced pigmentation using B16F10 melanoma cells, melan-a normal melanocytes, and three-dimensional human skin models." (PMID 35740060, 2022).
melanoma (continued). "SP has been reported to have anti-inflammatory effect and antioxidant effect, When B16F10 melanoma cells were treated with 0–50 μm SP, it was found that SP to induce melanin synthesis in a dose-dependent manner by increasing the expression of MITF and tyrosinase via increasing CREB phosphorylation." (PMID 34858164, 2021). "Kojic acid is only known to inhibit melanogenesis by direct inhibition of tyrosinase; however, it does not affect the expression of microphthalmia-associated transcription factor (MITF), which is engaged in proliferation and survival of melanoma cells." (PMID 34072104, 2021). "Indeed, when miR-125b was overexpressed in WM266-4 and MNT1 human melanoma cells, decreased levels of the melanogenic enzymes TYR and DCT were observed, although these genes are not direct miR-125b targets." (PMID 34198907, 2021). "In addition, WH-130 inhibited melanogenesis more effectively due to downregulation of tyrosinase in B16F10 melanoma cells than non-heated licorice extract." (PMID 34563052, 2021). "Therefore, the melanoma cells can still proliferate, but the tyrosinase is not functional due to inhibition of KA." (PMID 34072104, 2021). "However, variable levels of miRNA in stage III and IV melanoma indicate that blood tyrosinase level is not a dependable marker in metastatic disease." (PMID 34441278, 2021). "Besides directly inhibiting the activity of mushroom tyrosinase, dieckol also reduced the melanin content in α-melanocyte stimulating hormone (α-MSH)-elicited B16F10 melanoma cells, by the inhibition of murine tyrosinase, more effectively than the commercial agent arbutin." (PMID 33353007, 2020). "Several studies have previously shown that the expression of melanogenic enzymes (tyrosinase, TRP-1, and TRP-2) is transcriptionally regulated by MITF, resulting in a decrease in melanogenic enzyme expression and the inhibition of melanogenesis in B16F10 melanoma cells." (PMID 32630811, 2020). "PME promoted melanin production, tyrosinase activity, and the expression of melanogenic genes, such as MiTF and tyrosinase in B16F10 cells, as previously reported in mouse B16 cells, rat dermal papilla cells, human foreskin melanocytes, and human melanoma SK-MEL-18 cells and zebrafish." (PMID 32714420, 2020). "In this study, we aimed to investigate the inhibitory effect of IPA and IO crude extract (IOE) in tyrosinase activity and melanogenesis on α-MSH-induced zebrafish in vivo and B16F10 melanoma cells in vitro in order to evaluate their potential use in treating skin pigmentation and melanoma." (PMID 32957728, 2020). "In this study, we investigated whether coumaric acid- and caffeic acid-conjugated peptides might affect alpha-melanocyte stimulating hormone-induced melanin production, tyrosinase activity, and melanin synthesis-related gene expression in SK-MEL-2 human melanoma cells." (PMID 32625101, 2020). "In addition, other pigmentation markers including TYR and DCT serve as melanoma antigens." (PMID 32978520, 2020). "Current DC vaccination trials with melanoma patients use different types of tumor-associated Ags for loading of DCs for vaccination such as tumor lysate, tumor cell mRNA and several non-mutated self-Ags (e.g., gp100, MART1, tyrosinase)." (PMID 30764534, 2019). "Additionally, we reported a GH-induced upregulation and GHRKD-induced suppression of MITF-regulated melanogenesis pathway genes—TYR, TYRP1, TYRP2/DCT—as well as melanosomal markers PMEL (gp100) and MLANA, in multiple melanoma cell lines, xenograft models, and in silico analyses." (PMID 31547367, 2019). "Moreover, 974-A, phlorofucofuroeckol-A and eckol reduced the cellular melanin content and tyrosinase activity, and downregulated the expression of melanogenesis enzymes including tyrosinase, tyrosinase-related protein (TRP)-1, and TRP-2 in B16F10 melanoma cells." (PMID 31344959, 2019). "In this study, tyrosinase enzyme and mouse melanoma cells were used, and similar results thus may not be obtained with human cells." (PMID 31561511, 2019).
melanoma (continued). "In addition, a slightly lower expression of TyR was recorded above the stage III sample than above the stage III sample, which is considered to be the result of the homogeneous distribution of TyR in stage III melanoma." (PMID 30096895, 2018). "Hirata and co-workers had discovered that the natural product (−)-cubebin isolated from leaves of Piper nigrum L. wa sproved to have a stimulator effect on melanogenesis and tyrosinase activity in murine B16 melanoma cells without any significant effects on cell proliferation." (PMID 28777326, 2017). "The target sites of some TCM did not influence the tyrosinase activity, but might play a role on inhibiting cell proliferation of melanoma by other links of melanin metabolism." (PMID 29197358, 2017). "Surprisingly, lower plumbagin concentrations (0.5–1 μM) effectively inhibited melanin synthesis and tyrosinase activity but do not cause toxicity in keratinocytes, lens epithelial cells, and B16F10 mouse melanoma cells, suggesting that plumbagin is safe for dermal application." (PMID 28165370, 2017). "Furthermore, treatment of melanoma cells with a specific inhibitor of the MAPK pathway or overexpression of dominant negative mutants of MEK induce melanogenesis by increasing tyrosinase expression." (PMID 25903150, 2015). "Because the oxidation of RD to its quinone derivatives was speculated to be performed more possibly by intracellular tyrosinase than extracellular autoxidation, the oxidation process could closely relate to the intracellular production of ROS in B16F10 melanoma cells." (PMID 25861631, 2015). "Autolysate of Leuconostoc mesenteroides isolated from kimoto induced a decrease in melanin content in B16F0 murine melanoma cells through inhibiting tyrosinase activity, tyrosinase translation, or accelerating its degradation but did not inhibit tyrosinase activity under cell-free conditions." (PMID 25255749, 2014). "In support of this possibility a study of sixteen human melanoma cell lines demonstrated that MHC class II-expressing melanoma cells lack GILT expression and are unable to present an MHC class II-restricted epitope derived from the endogenous melanoma antigen tyrosinase." (PMID 24409178, 2013). "The observation that exogenous Mitf-M fails to reactivate the tyrosinase promoter in melanoma cells that have lost expression of Mitf-M suggests that Mitf-M might, likewise, not be able to activate the tyrosinase promoter in CCS cells." (PMID 12966428, 2003). "Tyrosinase mRNA amplification by reverse-transcriptase-polymerase chain reaction may be a useful tool for monitoring the efficacy of adjuvant treatment in stage IIB and III melanoma patients." (PMID 12107840, 2002). "Thus, it was found that the killing effect of 4-S-CAP is highly dependent upon the synthesis of melanin and tyrosinase in melanoma cells, suggesting that 4-S-CAP may become toxic to melanoma cells only after oxidation by tyrosinase." (PMID 1997095, 1991). "Although tyrosinase may not seem to be a preferred target in amelanotic canine melanoma when determined by immunohistochemistry, other techniques showed significant tyrosinase overexpression in both melanotic and amelanotic melanomas." (PMID 40284831, 2025). "One potential limitation of this study is that despite the presence of tyrosinase in both banana spots and melanoma lesions, our samples in this study do not contain malignant melanin pigmentation that could slightly modify the spectral similarity obtained in our current study." (PMID 39517908, 2024).